TNF (tumor necrosis factor)
Diseases named in the same sentence as TNF in open-access papers (continued):
Sharing a sentence is not in itself a finding about the gene and the disease.
tumor (continued). "It was demonstrated that the system showed sound therapeutic effects in melanoma mice, which may be related to the fact that VNP α TNF-α inhibited tumor progression by reducing tumor vascular density, inducing more apoptosis in tumor tissues, and activating the immune system." (PMID 37854883, 2023). "In conclusion, the bioinformatic analysis demonstrated that lncRNA LINC01207 may act as an oncogene that is highly expressed in CRC samples and associated with pathways such as ECM-receptor interaction, O-glycan processing, TNF signaling pathway in tumor growth, and metastasis." (PMID 36873741, 2023). "Moreover, macrophage‐derived TNFα can promote Wnt/β‐catenin signaling and may contribute to tumor development in Helicobacter‐infected gastric mucosa." (PMID 36420735, 2023). "Finally, manganese appeared to be a general immunostimulant in our study (higher IL-4, IL-12, TNFα), consistent with the effects of chronic manganese exposure on increased inflammatory, humoral, and anti-tumor activity in murine models and increased IL-1ß in pregnant women." (PMID 36429656, 2022). "In addition, we found that the ADP@SWNT/TNFα complex could inhibit tumor growth and metastasis both in vivo and in vitro and that the anti‐tumor effect was enhanced by NIR irradiation." (PMID 34994069, 2022). "Furthermore, this metabolic dysregulation is also mediated by pro-inflammatory cytokines originated by tumor by-products, as well as by the host immune system, in which tumor necrosis factor (TNF-α), interferon-gamma (IFN-γ), and several interleukins, including IL-6, are involved." (PMID 35457471, 2022). "In a xenograft mouse model, the polarization of the tumor-associated (M2) macrophage and the expression of breast cancer gene 1 (BRCA1), human epidermal growth factor receptor 2 (HER2), vascular endothelial growth factor (VEGF), and tumor necrosis factor (TNF)-α were measured." (PMID 36118080, 2022). "Interestingly, in BRCA1-deficient ovarian cancer models, PARP inhibition with olaparib increased CD4+ and CD8+ T cells in the tumor and in circulation, reduced their expression of inhibitory receptors PD-1, Tim-3, and Lag-3, and increased their levels of TNF-alpha and IFN-γ secretion." (PMID 36276148, 2022). "Nevertheless, the question if and how this cytokine can modify the chance of developing cancer and how anti-TNF therapy could interfere with the natural anti-tumor response, depending on the immunological context, is still being discussed in the medical community." (PMID 36358688, 2022). "Our experiments with a patient-derived cell model suggest that TGF-β signaling is required to induce the high-motility phenotype in tumor-derived reactive glia, whereas other pro-inflammatory cytokines like TNF-α may potentiate this phenotype by crosstalk with the NFκB pathway." (PMID 35803925, 2022). "In this study, we found that the pyroptosis genes including GSDMB, GSDME, NLRC4, NLRP2 and GZMA were hazardous genes in AML, and the genes of proinflammatory cytokines such as IL6 and TNF were found to be protective genes which maybe related with tumor microenvironment." (PMID 36553549, 2022). "Although scientists cannot exclude the possibility that the presence of a tumor increases the circulating inflammatory mediators, the findings suggesting the function of TNF and its receptors were of particular interest in view of the prospects of treatment with TNF inhibitors." (PMID 35628566, 2022). "Furthermore, these Vδ1 T cells produced TNF, IL-8, and granulocyte–macrophage colony-stimulating factor (GM-CSF), which attracted immunosuppressive myeloid-derived suppressor cells (MDSCs) into the tumor microenvironment to support immunosuppressive activity." (PMID 35740670, 2022).
tumor (continued). "The polysaccharides could activate macrophages, T-lymphocytes, B-lymphocytes, natural killer cells, and cytokines that are closely related to the killing of the tumor, such as tumor necrosis factor (TNF-α), interferon (IFN-γ), and interleukins (IL-2, IL-4, IL-6, and IL-12)." (PMID 35295918, 2022). "Hence, we wanted to examine if TNFα-treated BCSCs could also have an angiogenic effect on priming the premetastatic niche in the different organs of tumor-bearing mice." (PMID 36290384, 2022). "Moreover, TNF-α, as an activator of MMP, is associated with tumor progression." (PMID 35574296, 2022). "Furthermore, in situ detection of the corresponding genes, TNFRSF9, IFNG and TNF, may also be considered as a strategy to rapidly and efficiently identify the functional characteristics of most tumor-specific TILs based on scRNA sequencing data." (PMID 36451828, 2022). "Besides, RuPOP@CM can enhance the activity of cellular immune response and produce inflammatory cytokines in blood including IL-6, IL-12 and TNF-α, which is of great significance in treatment for circulating tumor cells from tumor metastasis or hematologic tumors." (PMID 36064356, 2022). "In addition, some earlier studies have also confirmed that these anti-metastatic effects could also contribute to the reduction in E-selectin, an endothelial leukocyte adhesion molecule, and the attenuation of TNF-α in tumor cell invasion." (PMID 36558925, 2022). "In addition, elevated levels of cytokines such as IL-6 or TNFα observed in certain tumor contexts can also induce epigenetic alterations, affecting to DNA components and histones, and modulating the expression of oncogenes and tumor suppressors through the NF-kB, JAK/STAT or p38MAPK pathways." (PMID 36004343, 2022). "In addition, we also found that cotreatment of BV6 with TRAIL and TNFα downregulates autophagy which could serve as a mechanism for the sidestepping of TRAIL/TNFα resistance in tumor cells with different apoptosis defects." (PMID 36358282, 2022). "In light of this knowledge, we hypothesized that there is a direct link between the metabolic reprogramming of cells undergoing tumor transformation and their specific response to TNF-α, resulting in increased migratory potential and consequently increased invasiveness and metastatic capacity." (PMID 36555705, 2022). "Mechanically, an inflammatory TME was the basis of immune-inflamed phenotype, also known as a hot tumor, containing pro-inflammatory cytokines which provided a more favorable condition for T cell activation and expansion, including type I and type II interferons, TNF-α, IL-2, and IL-12." (PMID 36276973, 2022). "Fourth, SBRT has been shown to enhance the magnitude of the immune response by producing more neoantigens, which could recruit a large number of T cells and promoted the release of inflammatory mediators related to tumor apoptosis, such as IFNγ, TNF-α, TGβ−1 and interleukins." (PMID 36084485, 2022). "Eosinophils can induce apoptosis and kill tumor cells via releasing ECP, EDN, TNF and granzyme, while mast cells may be damaging to tumor cells through cytokines and proteolytic enzyme secretion, indicating that COLCA1 may exert its tumoricidal functions through immunity." (PMID 35102554, 2022). "Mice with intrasplenic or portal injection of metastatic human CRC CX-1 cells showed an increase in TNF-α and IL-1α production by activated Kupffer cells, which resulted in an increase in the sinusoidal endothelial cell adhesion molecules and trans-endothelial migration of the tumor cells." (PMID 35954156, 2022). "Furthermore, anti-TNF-α treatment significantly inhibited tumor progression." (PMID 36140220, 2022). "Thus, the presence of TNF-α scarifying cells, such as macrophages, could promote the development of tumour cells." (PMID 35928364, 2022).
tumor (continued). "EPA treatment inhibited the mRNA expression of inflammatory cytokines including IL-1β, IL-6, MCP-1, and TNF-α in both the CaOV3 and SKOV3ip tumors, which was validated by similar decreased levels of these inflammatory cytokines in the serum from mice of both tumor models." (PMID 35326656, 2022). "However, cytokines released by tumor cells, such as G-CSF, IL-1β, IL-6, or tumor necrosis factor (TNF), have been proposed to prolong neutrophil lifespan, indicating that neutrophils may have a significant impact on cancer." (PMID 35784290, 2022). "Thus, TNF is known to promote tumor progression by enhancing the proliferation of tumor cells." (PMID 35401557, 2022). "Hence, TNF–α may be a link between neoplasia and inflammation by promoting cellular transformation, enhanced proliferation, prolonged survival, invasion and neoangiogenesis." (PMID 35886021, 2022). "To validate expression of IL-12 and test whether tracer administration impacts downstream IL-12/IL-12R signaling, we performed qRT-PCR on flash frozen tumor tissue to measure expression of IL-12β and key proinflammatory cytokines indicative of active IL-12 signaling: IFNγ, TNFα, and IL-18." (PMID 35634303, 2022). "Additionally, tumor volume and mass; thymus index; spleen index; the serum cytokines IL-2, IL-4 and TNF-α; IFN-ɤ levels and tumor histopathology could be detected as detection indicators." (PMID 36080446, 2022). "In CRC, the apoptosis-inducing properties of TNF are less pronounced compared with the pro-inflammatory properties that induce the production of several inflammatory cytokines, enhanced oncogene activation, tumor cell invasion and migration and creation of a tumor-supportive TME." (PMID 36611932, 2022). "The number of inflammatory substances in the tumor microenvironment is reduced, GC cell proliferation is deprived, apoptosis is promoted, and GC progression is retarded through controlling the IL-17 signaling route, TNF signaling pathway, and other inflammation-related pathways." (PMID 35321506, 2022). "Additionally, tissues treated with hMSCs showed a significant decrease of NK cell marker CD56 expression and an increase of TNF‐α and IL‐6 expression, which may contribute to tumor growth and metastasis." (PMID 34981659, 2022). "While counteracting tumor EV-decoy function might improve immunotherapy efficacy the same EV property might be advantageous when used therapeutically to neutralize the activity of inflammatory molecules such as IL-6 or TNFα." (PMID 35563789, 2022). "These screens indicated that TNFα-mediated tumor cell killing induced by cytotoxic T lymphocytes and NK cells plays a critical role in antitumor immunity, and tumor cells may take advantage of pro-survival TNFα signaling to avoid TNFα-mediated cell death during immune surveillance." (PMID 36071040, 2022). "Additionally, Th1 cell-derived IFN-γ induces enhanced production of tumorotoxic nitric oxide and TNF-α in tumor-infiltrated macrophages while Th17 cell-sourced IL-17 stimulate production of CXCL16 in tumor DCs, enabling increased recruitment of tumoricidal CCR6-expressing CD8+CTLs." (PMID 35757015, 2022). "Additionally, IL-6 plays a role in the recruitment of immune cells within the tumor microenvironment, thereby stimulating the production of other pro-inflammatory cytokines, including IL-1β, IL-8, and TNFα, thus providing a link between the inflammatory process and tumor progression." (PMID 35053592, 2022). "Moreover, the reactive oxygen species by nanocatalyzed tumor therapy increased the secretion levels of key cytokines, such as the interferon and tumor necrosis factor as well as tumor-specific antigens, thus activating the corresponding CAR T cells at the tumor site." (PMID 35401561, 2022). "However, even without a specifically defined mechanism, the assumption that TNF could act as a cytotoxic molecule was central to the hypothesis that this cytokine was effective as an anti-tumor agent." (PMID 36358688, 2022).
tumor (continued). "To determine whether the anti-tumor effect of the active ingredients of YFBP is associated with the regulation of the expression of the inflammatory mediator, we assessed the gene expression of TNFα, IL-1β, and IL-6." (PMID 36353478, 2022). "In addition, mast cells support tumor invasiveness by their immunosuppressive activity, releasing tumor necrosis factor-alpha (TNF-α), histamine, and interleukin-10 (IL-10) and suppressing T cells and natural killer (NK) that in turn induce immune tolerance mediated by regulatory T cells (Treg)." (PMID 35140718, 2022). "Cytokines such as tumor necrosis factor (TNF) and interleukins (ILs) are closely associated with the differentiation and proliferation of tumor cells and the formation of tumor neovascularization, which has an important impact on the progression of patients with tumor." (PMID 36226059, 2022). "TNF-α could also be produced by tumor cells and act as an endogenous tumor promoter or suppressor." (PMID 35453307, 2022). "In addition, the combined blockade of TIGIT and PD-1 further increased the level of infiltrating CD8+ T lymphocytes in the tumour tissue and secretion function factors TNF-α and IFN-γ by CD8+ T lymphocytes compared with the group subjected to TIGIT blockade alone." (PMID 35729552, 2022). "Moreover, the activation of TNF‐α by MMPs contributes to tumor progression." (PMID 36776395, 2022). "In a study investigating the role of TNF in liver metastasis with the help of TNFR1 and TNFR2 knockout mice, it was found that TNFR2 deficiency, but not lack of TNFR1, results in a significant reduction in liver metastasis in colon and lung carcinoma tumor model." (PMID 35681583, 2022). "Indeed, dual staining of KPC tumor showed that most of the TNF-α colocalized with F4/80+ macrophages, and analysis of RNA-Seq data showed strong expression from TAMs, validating the conclusion that macrophages are a primary source of TNF-α in PDA, consistent with previous findings." (PMID 36256464, 2022). "TNF-α, in addition to further damaging of mucosal barrier of intestine, can enhance the recruitment of other immune cells to lamina propria and stimulate the production of other inflammatory cytokines by attaching to its receptors on the epithelial cell surface as well as pre-tumor cells." (PMID 35410210, 2022). "Therefore, we speculated that although cytokines such as TNF-α can up-regulate PD-L1 on the tumor cells surface, some components from PSB could down-regulate PD-L1 expression, resulting in the constant levels of PD-L1 in the final tumor tissue." (PMID 35705974, 2022). "This confirms that TNFα in GBM cells may play an important role in tumor progression." (PMID 35626018, 2022). "We then measured the capacity for sgNT or sgNkg7 OT-I T cells to kill MC38-OVA or MC38-OVA-Tnfrsf1a-/- tumor cells in 4 hours (when tumor cell death is mediated by the perforin-granzyme pathway) or 18 hours (when tumor cell death is mediated by both the perforin-granzyme and TNF pathways)." (PMID 35874669, 2022). "Such molecules, including TNF-α and IL-1, play an important role for tumor progression because their upregulation triggers the expression of adhesion molecules (e.g., e-selectin and vascular cell adhesion molecule-1) on endothelial cells, which act as mediators for tumor growth." (PMID 36077144, 2022). "The frequencies of CD4+TNF-α+ and CD4+TNF-αhi negatively were associated with poor prognostic factors such as LN involvement (P = 0.015 and P = 0.019, respectively), stage of the disease (P = 0.032 and P = 0.010, respectively) and tumor size (P = 0.026 and P = 0.032, respectively)." (PMID 36376825, 2022). "Nonetheless, some studies have recently addressed a controversial role of TNF-α, showing pro-apoptotic and anticarcinogenic functions towards different tumor types, which could also be dependent on TME or specific conditions such as the TNFR that controls the pathway or the ER/PR molecular BC type." (PMID 35681689, 2022).
tumor (continued). "The findings revealed that a single dose of this transformable hydrogel could remarkably upsurge the frequency of specific CD8+ IFN-γ+ T cells and release TNF-α, thereby inhibiting tumor growth and generating antigen-specific antibodies that prevent metastasis occurrence." (PMID 36010836, 2022). "AIM2, CASP3, NLRC4, TNF, and NLRP6 may be associated with tumour drug resistance." (PMID 35246158, 2022). "TNF-α could enhance the sensitivity of tumors to treatment and promote apoptosis in the tumor." (PMID 36428767, 2022). "MC-C tumor immunogenicity was associated with the capacity of MC-C tumor lysate to promote the maturation of DC as evaluated by the up-regulation of cell surface receptors CD80, CD86 and MHC II as well as production of the inflammatory cytokines TNF-α and IL-12p70." (PMID 35922755, 2022). "Moreover, the upregulation of TNFRSF1B, TNFRSF8, TNFRSF9, and TNFRSF10 expression, as well as elevated levels of TNF, suggested apoptotic signal transition through the TNF family membrane receptors, which was also detected in tumour cells treated with chemotherapeutic drugs." (PMID 35804353, 2022). "HCC tumor tissues with high glycolytic macrophages showed higher glycolysis rates, produced more lactate, and mediated the upregulation of PD-L1 induced by inflammatory factors such as TNF-α, blocking TNF-α which could inhibit the expression of PD-L1 in 40%-50% of tumor macrophages." (PMID 36686771, 2022). "The results suggest that the anti-tumor mechanism mediated by αCTLA-4 treatment in the IM vaccination may skew the neoantigen-specific immune response toward a CD8+IFNγ+ effector function whereas in the ID vaccination in the direction of CD4+TNFα+." (PMID 35110563, 2022). "Consequently, TNFα coding sequences have been added to an oncolytic adenovirus with an Ad5/3 chimeric capsid and a 24 bp deletion in the constant region 2 of E1A to make virus replication selective for tumor cells with a defective retinoblastoma/p16 pathway." (PMID 35155581, 2022). "The combination of multiple cytokines may have a greater tumor-promoting effect than a single cytokine; for example, TGFβ1 leads to demethylation of PD-L1 promoter and TNFα leads to the expression of demethylated promoter and co-induces the overexpression of PD-L1." (PMID 35582541, 2022). "Tumor-associated macrophages increase AMP-activated protein kinase (AMPK) and peroxisome proliferator-activated receptor-gamma coactivator 1α (PPARγC1α) in the macrophages to facilitate tumor hypoxia and produce tumor necrosis factor (TNF)α to enhance tumor cell glycolysis." (PMID 36233088, 2022). "The results obtained in vivo showed that through local reduction of oxidative stress and inflammation (IL-1β, TNF-α), the Emorsan® Gel significantly reduced the infiltration of mast cells into the injured wound, leading to the amelioration of symptoms such as itch and skin irritation." (PMID 35563099, 2022). "Interestingly, TNF-α was upregulated while IL-6 was downregulated in the tumor microenvironment." (PMID 35418151, 2022). "Moreover, with an increasing number of studies focusing on TNF, its roles in fibroblasts within the tumor microenvironment have gradually become more precisely elucidated, and it has accordingly been established that its functions are not confined to merely driving fibroblast activation." (PMID 36263225, 2022). "However, studies on the TNF-α/TNFR1/ANXA1 axis with respect to tumours are rare." (PMID 35415239, 2022). "For example, the Se-enriched Grifola frondosa polysaccharide could enhance the thymus and spleen indices of the tumor-bearing mice, increase both serum tumor necrosis factor-α (TNF-α) and interleukin-2 (IL-2) levels, and also promote nitric oxide (NO) production and macrophage phagocytosis." (PMID 36235602, 2022). "In addition, high expression of TNF and NF-κB in tumor microenvironment promotes survival in HCC." (PMID 36555597, 2022).